CXCR4 (C-X-C motif chemokine receptor 4)
Diseases named in the same sentence as CXCR4 in open-access papers (continued):
Sharing a sentence is not in itself a finding about the gene and the disease.
cancer (continued). "While CXCR4 is reported to be overexpressed in multiple human cancer types and many hematological cancer cell lines, we have observed poor in vitro cell surface expression of CXCR4 in many solid tumor cell lines." (PMID 25514788, 2014). "Several studies have implicated a role for chemokine receptors, in particular CXCR4 and CCR7, in cancer progression and metastasis." (PMID 24594697, 2014). "Its function in metastasis begins with cancer cell mobility—the binding of CXCL12 to CXCR4 activates various intracellular signal transduction pathways and effector molecules that regulate chemotaxis, migration, and adhesion." (PMID 25165728, 2014). "Although reports of various cancer types showing high levels of CXCR4 expression, we have experimentally observed that cell lines of various solid tumors exhibit weak cell surface CXCR4 expression in vitro." (PMID 25514788, 2014). "The initial model suggested that cancer cells hijack CXCR4, allowing the malignant cell to follow endocrine gradients of ligand produced by distant tissues." (PMID 24594697, 2014). "Mounting evidence from various laboratories has indicated that malignant tumors, in contrast to benign tumors, express a high level of CXCR4 and the level of CXCR4 is correlated with metastasis to distant organs and reduced overall survival." (PMID 24659999, 2014). "A better understanding of the signaling pathways and transcriptional factors involved in regulating CXCR4 expression is essential in elucidating the role of CXCR4 in cancer." (PMID 25514788, 2014). "Analysis of a cohort of colon polyps and chromosome-unstable carcinomas showed that the expression of CXCR4 and CXCR7 was similar to that of the normal mucosa in the polyps and early-stage carcinomas but significantly increased in late stage carcinomas." (PMID 24629239, 2014). "Blocking TEM recruitment either using CXCR4 antagonist plerixafor or by genetic TEM depletion markedly enhanced the efficacy of CA-4-P treatment in subcutaneous N202 (Neu+) mammary/carcinoma model." (PMID 25051364, 2014). "Although the SDF-1/CXCR4 system mainly functions as a chemotactic factor in cancer cells, it is also involved in the several metastatic processes, such as neovascularization, cell adhesion, invasion, outgrowth and epithelial to mesenchymal transition." (PMID 24236200, 2013). "The CXCR4/CXCL12 axis plays a role in cancer metastases, stem cell mobilization and chemosensitization." (PMID 24058588, 2013). "Stromal cell derived factor 1α (SDF-1α), which is a well-established chemo-attractant for leukocytes, acts directly on cancer cells by stimulating proliferation through the SDF-1α receptor chemokine (C-X-C motif) receptor 4 (CXCR4) expressed on cancer cells." (PMID 24348516, 2013). "In this study, we examined the putative in vitro and in vivo anti-cancer effects of the specific CXCR4 inhibitor AMD3465." (PMID 23484027, 2013). "In contrast, PDACs showed increased levels of CXCR4; this is a well-established feature of many cancer types and is a predictor of poor survival in PDAC." (PMID 23372777, 2013). "In conclusion, the data presented provides the first clear evidence of CXCR4 located at the nucleus of cancer cells and existing as a functional, ligand-responsive receptor in advanced metastatic PCa cells." (PMID 23468933, 2013). "In view of the significant role that CXCR4 activation plays in cancer and other diseases, identification of novel small molecule antagonists, which would have an appropriate profile for clinical progression, has gathered pace in recent years." (PMID 24205302, 2013). "Amongst the chemokine signalling axes involved in cancer, chemokine CXCL12 acting on chemokine receptor CXCR4 is particularly significant since it orchestrates migration of cancer cells in a tissue-specific metastatic process." (PMID 24205302, 2013). "CXCL12 was also commonly affected; it plays a role in cancer spread/metastases via interaction with its receptor CXCR4." (PMID 23372777, 2013).
cancer (continued). "CXCR4 is a transmembrane G protein-coupled receptor, which has gained recent interest in the cancer metastasis world." (PMID 26237063, 2013). "The slow cycling subpopulation in GBM cells, which is enriched with cancer stem cell markers, showed increased levels of cell surface CXCR4 and CXCR7." (PMID 23555768, 2013). "CXCR4 plays critical roles in the proliferation and migration of granule cell neuron precursors during development, and is involved in cancer metastasis." (PMID 23497290, 2013). "A close relationship between phosphoglycerate kinase 1 (PGK1) and the CXCR4/SDF1 axis (chemokine receptor 4/stromal cell derived factor 1) has been shown for several cancers." (PMID 24376734, 2013). "The chemokine receptor CXCR4 is over-expressed in many cancer types and is also involved in their proliferation." (PMID 24259307, 2013). "The predominant SDF-1α receptor is believed to be CXCR4, and signaling through CXCR4 alters the ability of cancer cell lines to adhere to the endothelium and invade through the extracellular matrix components, such as MMP-9, in the bone marrow." (PMID 24094005, 2013). "The dysregulated expression of CXCR4 was detected in several human cancers that included melanoma, breast, pancreatic and CRC." (PMID 24330809, 2013). "The CXCR4-SDF-1 complex has been implicated in cancer cell migration and metastasis, and is a therapeutic target in cancer treatment." (PMID 23472106, 2013). "CXCR4 has been reported to be widely expressed and to exert large-scale effects in cancer cells by participating in multiple cellular processes, including cell invasion-related signaling." (PMID 24330809, 2013). "The involvement of CXCR4 in cancer metastasis appears to be due to dysregulation of the receptor leading to enhanced CXCR4 signaling." (PMID 23497290, 2013). "Recent studies have demonstrated that MIF and CXCR4 were overexpressed in a number of cancers, including gastric cancer, breast cancer, prostate cancer, colon cancer and nasopharyngeal carcinoma." (PMID 23497377, 2013). "Certain chemokines and their receptors, in particular stromal cell-derived factor (SDF)-1α and CXC chemokine receptor 4 (CXCR4), are involved in cancer cell migration, proliferation, and survival." (PMID 25285238, 2013). "A total of 28 articles including 5,583 invasive cancers reported on CXCR4 expression, with a range of 7 to 1,808 cancers per study." (PMID 24206539, 2013). "The chemokine receptor CXCR4 regulates cell migration during ontogenesis and disease states including cancer and inflammation." (PMID 23734232, 2013). "This pathway was also involved in the increase CXCR4 mRNA expressed by the cancer cells upon their co-culture with macrophages." (PMID 24384839, 2013). "SDF-1/CXCR4 system mainly functions as a chemotactic factor in cancer cells to reach metastatic sites." (PMID 24236200, 2013). "Some of the upregulated genes are related to CSC/’cancer stemness’ such as CXCR4, CD133, EPCAM and SOX9, while others are associated with apoptosis (FASLG, TJP2, DUSP4), the MAPK pathway (MAP2K4, DUSP4), and chemoresistance (MMP1, an ETS1 target gene)." (PMID 24069258, 2013). "EGFR is involved in invasion and metastasis of several human carcinomas, and correlates directly with CXCR4 expression." (PMID 23472069, 2013). "This is consistent with the reported over-expression of CXCR4 through A2A and A2B receptors in human carcinoma cells." (PMID 23326587, 2013). "The stromal cell-derived factor-1 (SDF-1) and its receptor, CXCR4, have been reported to be related to stem cell homing and cancer cell metastasis." (PMID 22634835, 2012). "A growing body of evidence has demonstrated that CXCR4 plays an important role in cancer proliferation, dissemination, invasion and drug resistance." (PMID 22359577, 2012). "A survival curve was used to explore the correlation between the content of CD133+CXCR4+ cancer cells and patient survival." (PMID 22871210, 2012).
cancer (continued). "Expression of CXCR4 in cancer cells generally activates the Akt-signaling pathways that are responsible for cellular invasion and proliferation." (PMID 23342263, 2012). "CXCR4 is overexpressed in more than 20 different human cancers, and therefore has been proposed as a prognostic factor and therapeutic target." (PMID 22685650, 2012). "The role of CXCR4 in cancer progression has generally been analyzed in the context of cancer cell metastasis." (PMID 22359577, 2012). "Several lines of evidence support the clinical relevance of this chemokine receptor by demonstrating that CXCR4 promotes angiogenesis and site specific cancer metastasis to the favorable organs, where its ligand CXCL12 is abundantly expressed." (PMID 23071744, 2012). "In initial attempts to image CXCR4 expression in cancer models, researchers evaluated 111In-labeled peptides and 125I-labeled monoclonal antibodies with SPECT/CT." (PMID 22685650, 2012). "Among the chemokine receptors, CXCR4 is the most involved in cancer, as it is expressed in at least 23 different types of cancers." (PMID 22399057, 2012). "CXCL12-CXCR4 axis plays protumoral roles in many types of cancers, and intensive studies have been done to explore the therapeutic approaches that target CXCR4-mediated cancer invasion and metastasis." (PMID 24213462, 2012). "CXCR4 is expressed by fibroblasts, endothelial, hematopoietic cells and stromal cells, in different types of cancer cells, such as BC cells, and in numerous types of embryonic and adult stem cells (SCs), which can be chemoattracted by its ligand, SDF-1." (PMID 22709548, 2012). "Recent studies have shown the involvement of the CXCL12/CXCR4 axis in the progression of several types of cancer." (PMID 23181100, 2012). "Of relevance to this study, CXCR4, a seven-transmembrane span G-protein-coupled receptor expressed in multiple normal and cancer stem cells was expressed 2.63-fold higher in the cluster cells." (PMID 22349813, 2012). "Nuclear localization of CXCR4 has been described, and demonstrated to correlate with disease progression, in several distinct cancer types." (PMID 23249693, 2012). "SDF-1 also modulates adhesion of CXCR4-positive cancer cells to endothelial cells, to fibrinogen and to fibronectin by activating specific integrins and other cell surface molecules including VCAM-1, ICAM-1 on endothelial cells." (PMID 22676510, 2012). "Of the numerous expressed chemokine receptors, CXCR4 is the most highly expressed in MM and many other cancer cells." (PMID 23251606, 2012). "Compared with CD133+CXCR4- cells, CD133+CXCR4+ cancer cells experienced EMT, which contributed partly to their metastatic phenotype." (PMID 22871210, 2012). "For some malignant tumors, CXCR4 plays important roles in cell chemotaxis movement, which is essential for metastasis and inhibited by K5." (PMID 23300882, 2012). "SDF-1 also promotes adult NPC proliferation as well as migration, and the SDF-1/CXCR4 signaling axis is involved in trafficking of normal stem cells as well as in metastasis of cancer cells." (PMID 22539956, 2012). "This is in line with our findings that the corresponding alteration in mRNA expression levels of EMT-related genes and higher migratory and invasive capacities have been observed in CD133+CXCR4+ cancer cells." (PMID 22871210, 2012). "CXCR4 showed a predominantly nucleolar distribution in the cancer cells (48/97, 49.5%), with a cytoplasmic distribution in 24 cases (24/97, 24.7%) and a membrane distribution in 25 (25/97, 25.8%)." (PMID 23039915, 2012). "The expression of CXCR4 has been detected in 23 different types of cancers, making it the most common chemokine receptor expressed on cancer cells." (PMID 22485156, 2012). "A number of cancer molecular markers associated with bone metastasis were assessed by immunohistochemical technique, including PTHrP, OPN, c-Src, MMP2, CXCR4, PI3K, BSP, NFκB, IGF-1R, and BMP4." (PMID 22537906, 2012).
cancer (continued). "Taken together, our data demonstrate that CD133+CXCR4+ cancer cells are possible migratory CSC subtypes in CRC." (PMID 22871210, 2012). "Immunoblot and immunohistochemistry with the anti-phospho-PKCζ or anti-phospho-CXCR4 antibody further confirmed that PKCζ-shRNA reduced the expression of phosphorylated PKCζ and HGF-induced phosphorylated CXCR4 in cancer cells of the MDA-MB-436 xenografts." (PMID 22242160, 2012). "CXCR4 expression can be upregulated in cancer cells via a number of pathways, for example, hypoxia, VEGF, oestrogen, and stimulation of the transcription factor NF-κB pathway." (PMID 22272201, 2012). "This indicated that CD133+CXCR4+ cancer cells are a subpopulation of CSCs with a metastatic phenotype." (PMID 22871210, 2012). "In this regard, rGel/BLyS was recently shown to eliminate circulating cancer cells in a mouse model of disseminated BCP-ALL, but had little effect on cancer cells in the bone marrow unless these cells were mobilized using a CXCR4 antagonist." (PMID 23056634, 2012). "The transendothelial migration is further facilitated by SDF-1 induced secretion of matrix metalloproteinases (MMP)-2 and MMP-9 by CXCR4 positive cancer cells." (PMID 22676510, 2012). "There is a significant volume of literature demonstrating that CXCR4 and CXCL12 play critical roles in cancer metastasis in numerous types of cancers and it is important to develop anti-CXCR4 compounds to intervene in this progression." (PMID 22485156, 2012). "The CXCL12/CXCR4 pathway was originally discovered in the immune system to play an important role in cancer cell metastasis." (PMID 22074556, 2011). "Of the numerous chemokine receptors that are expressed, CXCR4 is the most highly expressed chemokine receptor in many cancer cells." (PMID 21912642, 2011). "Although the contribution of SDF-1/CXCR4 axis is reported in some cancer cells or leukemic niches such as bone marrow, we demonstrated that this axis works even in the extramedullary niche of leukemic cells." (PMID 22069486, 2011). "The mTOR pathway has been linked to cancer cell migration and our data support a model of signal cross-talk between CXCR4 and mTOR during cancer cell metastasis." (PMID 21949786, 2011). "In model systems, CXCR4 regulates cancer metastasis to lymph node, bone, liver, and lung, the four most common metastatic destinations, which also express high levels of CXCL12, the only known chemokine ligand for CXCR4." (PMID 21672222, 2011). "SDF-1 and its receptors, such as CXC chemokine receptor 4 (CXCR4), are thought to play critical roles in motility, homing, and proliferation of many cancer cells." (PMID 21909361, 2011). "In PAC stem cells (defined as CD133 positive), CXCR4 was markedly overexpressed in comparison with others cancer cells." (PMID 24212636, 2011). "The CXCL12/CXCR4 axis seems involved in angiogenesis, metastasis, and survival; cancer cells expressing CXCR4 migrate and spread along the CXCL12 gradients." (PMID 24212636, 2011). "It has been well documented that the CXCL12/CXCR4 signaling cascade plays a crucial role in cancer proliferation, migration and metastasis." (PMID 21880153, 2011). "The CXCR4/CXCL12 axis can coordinate metastasis of a variety of cancers, such as bladder, breast, head and neck, ovarian, renal cell, and prostate." (PMID 22074556, 2011). "Osteopontin and CXCR4 have been used as markers for immune activation for homing precursor cells and for metastasizing cancer cells." (PMID 21909361, 2011). "This assumption is augmented by the findings revealing that several CXCR4+ cancers such as breast, ovarian and prostate cancer metastasize to bones from bloodstream in a SDF-1 dependent fashion." (PMID 21342498, 2011). "Overall, our results indicate, for the first time, that plumbagin is a novel blocker of CXCR4 expression and thus has the potential to suppress metastasis of cancer." (PMID 21880153, 2011).
cancer (continued). "Double CXCR4/FOXP3 immunoperoxidase staining was performed to evaluate CXCR4 positive Treg infiltration in whole stained sections from 10 grade 3 basal-like and 11 grade 3 luminal cancers." (PMID 21521526, 2011). "This ligand offers the possibility to be used as an initial tool for diagnosis in an approach of personalized medicine for treating CXCR4-related cancer." (PMID 21780290, 2011). "The preferential expression of cancer stem cells related marker (CXCR4), regulatory genes (BMI1, GLI1, and GLI2) and microRNAs (miR-214, miR-21, miR-221, miR-222 and miR-155) in holoclones were also highlighted." (PMID 21826251, 2011). "Exposure of CXCR4+CXCR7+ cancer cells to CXCL12 greatly potentiated their TEM towards the chemokines CCL19 and CXCL13." (PMID 21672222, 2011). "Some of them are implicated in the development or progression of cancer, in particular the chemokine CXCL12 (also termed stromal cell-derived factor-1, SDF1) which binds to two receptors, the CXC receptor 4 (CXCR4) and the CXC receptor 7 (CCR7)." (PMID 24212636, 2011). "In another study, CD133+CXCR4+ cancer stem cells derived from human pancreatic cancer tissue were highly resistant to standard chemotherapy." (PMID 24281171, 2010). "HSP27 was also selected due to spectral counts indicative of phosphorylation upon CXCL12 activation of CXCR4, its implications in cancer and protection from apoptosis, and the availability of a phospho-specific antibody at the Ser82 phosphorylation site." (PMID 20661426, 2010). "The chemokine receptor, CXCR4, is expressed in a variety of malignancies and has been extensively studied for its role in cancer pathogenesis." (PMID 21045835, 2010). "After further research on the receptor, investigators found that CXCR4 is one of the most comprehensive cytokine receptors expressed in tissue, playing an important role in the growth and metastasis of a variety of malignant tumors." (PMID 21110890, 2010). "In particular the imbalanced or aberrant expression of CXCL12 and its receptor CXCR4 strongly affects cancer cell proliferation, recruitment of immunosuppressive cells, neovascularization, and metastasization." (PMID 20049170, 2010). "Certainly, in vivo studies have confirmed this theory with CXCR4 inhibition in mouse models of cancer showing decreased metastases." (PMID 20492653, 2010). "The cancer cells were positive for CXCR4, CXCL12, HER1, HER4 (a chemotactic receptor that responds to HB-EGF), and GM-CSF." (PMID 20946648, 2010). "The expression of CXCR4 in HCC tissue was significantly lower than in carcinoma inflammatory liver tissue." (PMID 21110890, 2010). "Carcinomas frequently have elevated CXCR4 expression, which is a key regulatory element in enabling tumor cell metastasis, a locomotory event characteristic of migrating immune cells." (PMID 20877573, 2010). "In carcinoma, CXCR4 expression mediates metastasis to bone, which has relatively high levels of SDF1." (PMID 20102637, 2010). "Considering the importance of CXCR4 in a variety of cancers, attempts have been made to blockade this molecule as a therapeutic target." (PMID 19671192, 2009). "Hypoxia, and particularly HIF-1α, has also been shown to regulate the expression of CXCR4 in cancer, including NSCLC." (PMID 19563666, 2009). "The CXCR4/CXCL12 biological axis has been postulated to have an important in supporting cancer stem cells." (PMID 19563666, 2009). "We found that SDF-1α stimulated the invasion of E6/E7-positive cancer cell lines (HeLa and TC-1) in Matrigel though CXCR4 and subsequent Rho/ROCK activation." (PMID 19325708, 2009). "ILC cells with activated c-Src co-expressed metastatic markers (Opn, Cxcr4) and included cells positive for the cancer stem cell marker Aldh1." (PMID 19583841, 2009). "More recent studies have suggested that CXCR4 is expressed on various other cancer cells and its expression stimulated migration of cancer cells towards a CXCL12 gradient established in specific target organs for metastases." (PMID 19563666, 2009).